ACE (angiotensin I converting enzyme)
Diseases named in the same sentence as ACE in open-access papers (continued):
Sharing a sentence is not in itself a finding about the gene and the disease.
sexual dysfunction (4 papers, 2020 to 2024). Disturbances in sexual desire and the psychophysiologic changes that characterize the sexual response cycle and cause marked distress and interpersonal difficulty. "Diuretics were second to CCBs concerning the tendency of association with sexual dysfunctions, while ACE inhibitors were the next most frequent class of antihypertensive medications associated with sexual dysfunctions." (PMID 32670607, 2020). "In this study, it was found that CCBs use was associated with the highest occurrence of sexual dysfunctions, followed by diuretics, ACE inhibitors and centrally acting antihypertensives." (PMID 32670607, 2020). "Furthermore, it was observed that the use of calcium channel blockers CCBs was associated with the highest occurrence of sexual dysfunctions, followed by diuretics, ACE inhibitors and centrally acting antihypertensives." (PMID 32670607, 2020). "The combination of diuretic + ARB stands out, as 83.9% of patients reported sexual dysfunction; this was followed by ACE inhibitor monotherapy (77.8%)." (PMID 34830496, 2021). "Clinically relevant sexual dysfunction was observed with the ACE inhibitors (55.5%) and the diuretic + calcium antagonist combination (43.8%)." (PMID 34830496, 2021). "Beta-blockers and ACE inhibitors are classes of medication which have previously been associated with sexual dysfunction in men with CHD in some but not all studies, in keeping with our findings." (PMID 34869122, 2021). "The ACE inhibitors (55.51%) and the combinations ARB + calcium antagonist (50.1%), diuretics (35.7%) + calcium antagonists and diuretics (50.1%) and ARBs + diuretics (50.1%) were those that produced clinically relevant sexual dysfunction." (PMID 34830496, 2021).
skin cancer (4 papers, 2013 to 2025). "This may be of clinical relevance, since it has been reported that the use of ACE inhibitors is correlated with a lower incidence of skin cancer." (PMID 24223058, 2013). "The rate of intake of HCT or ACE inhibitors is significantly higher in our patient collective with non-melanotic skin cancer compared to the group from the age-matched general population (DAK insured (p < 0.001)) compared to the routine data of the DAK-G." (PMID 35175408, 2022). "Furthermore, the rate of intake of HCT or ACE inhibitors in the comparison group from the general population (DAK insured) is significantly lower than in our patient collective with non-melanotic skin cancer (p < 0.001)." (PMID 35175408, 2022).
thyroid (4 papers, 2017 to 2020). "This study was conducted to find out the various effects of angiotensin-converting enzyme inhibitors (ACE inhibitors) (Fosinopril) and direct renin inhibitors (Aliskiren) on the RAAS system in rats with thyroid disorders." (PMID 31396276, 2019).
type 2 diabetic nephropathy (4 papers, 2011 to 2024). "Several studies showed the association of ACE (angiotensin I converting enzyme (peptidyl-dipeptidase A) 1) variants with AD as well as type 2 diabetic nephropathy, and cerebral amyloid angiopathy-related lobar intracerebral hemorrhage recurrence." (PMID 23894628, 2013). "Multiple lines of evidence suggest that the ACE DD genotype is associated with reduced renal benefit from ACE inhibitor treatment in patients with type 1 or type 2 diabetic nephropathy." (PMID 23049672, 2011). "The ACE I/D polymorphism therefore appears to be a useful test to predict the progression of type 1 or type 2 diabetic nephropathy." (PMID 23049672, 2011). "Furthermore, the ACE I/D polymorphism is a useful test to predict the progression of type 1 or type 2 diabetic nephropathy and also to predict benefit from ACE inhibitor treatment." (PMID 23049672, 2011).
vascular dementia (4 papers, 2005 to 2020). A degenerative vascular disorder affecting the brain. "Hence, the combination of curcumin treatment with ACE inhibitors, especially perindopril for the inhibition of ACE and AChE activity in the brain is a better intervention in hypertensive patients with the risk of vascular dementia." (PMID 31739443, 2019).
Adrenal insufficiency (3 papers, 2013 to 2024). Insufficient production of steroid hormones (primarily cortisol) by the adrenal glands. "Hyperkaliemia can be triggered by antihypertensive drugs (e.g., angiotensin-converting enzyme [ACE] inhibitors and sartans) as well as renal or adrenal insufficiency." (PMID 37017694, 2023).
amnesia (3 papers, 2021 to 2024). Pathologic partial or complete loss of the ability to recall past experiences ( AMNESIA, RETROGRADE) or to form new memories ( AMNESIA, ANTEROGRADE). "Both AT1R antagonists and ACE inhibitors reduced the effects of scopolamine-induced amnesia in rats submitted to the elevated plus-maze to test for working memory." (PMID 34451870, 2021). "The use of scopolamine to temporarily disrupt the neurotransmission by occupying the acetylcholine binding site in the muscarinic receptors induces amnesia, which is generally used in AD animal models and human clinical trials for developments of ACE inhibitors." (PMID 35203483, 2022). "Bioactivities such as antioxidative, ACE-inhibitory, DPPIV-inhibitory, anti-amnesia, and renin-inhibitory activities were identified from the nine proteolyzed proteins." (PMID 39200521, 2024).
ankylosing spondylitis (3 papers, 2012 to 2021). An autoimmune chronic inflammatory disorder characterized by inflammation in the vertebral joints of the spine and sacroiliac joints. "In this study, we assessed the effects of one-year anti-TNF therapy on ACE and ACE2 production in RA and ankylosing spondylitis (AS) in association with other biomarkers." (PMID 35155468, 2021).
anxiety disorder (3 papers, 2016 to 2022). A category of psychiatric disorders which are characterized by anxious feelings or fear often accompanied by physical symptoms associated with anxiety. "Estimating the effect of ACE inhibitors on a more granular level, we found that the effect was almost entirely driven by anxiety disorders, with very low incidence of phobias in any treatment arm of the cohort." (PMID 35689299, 2022).
artery stenosis (3 papers, 2020 to 2023). "In cases of unilateral renal artery stenosis, ACE inhibitors can safely be used, although they are not recommended in cases of bilateral renal artery stenosis or solitary functioning kidney." (PMID 33194923, 2020).
Brain atrophy (3 papers, 2014 to 2025). Partial or complete wasting (loss) of brain tissue that was once present. "The Rotterdam study examined the ACE genotype in relation to brain atrophy (which is associated with increased brain Aβ plaques), and found that female I/I genotype carriers had smaller hippocampal and amygdalar volumes." (PMID 24987467, 2014).
breast tumors (3 papers, 2012 to 2021). "Our algorithm predicted that breast tumors with lower ACE expression are more sensitive to bleomycin than those with higher expression." (PMID 33858332, 2021). "Most components of the RAS including angiotensinogen, angiotensin converting enzyme (ACE) and angiotensin receptors are expressed locally in a wide variety of tumors, including in breast tumors." (PMID 22536420, 2012).
Cerebral ischemia (3 papers, 2009 to 2015). Restriction of arterial blood supply to the brain associated with insufficient oxygenation to support the metabolic requirements of the tissue. "A protective effect of ARBs in cerebral ischemia has been largely documented, and has been shown to be dependent upon non-AT1 receptors, whereas ACE inhibition was deleterious or ineffective." (PMID 25888905, 2015).
cervical carcinoma (3 papers, 2020 to 2023). A carcinoma arising from either the exocervical squamous epithelium or the endocervical glandular epithelium. "Previously, an enhanced ACE activity was verified in tumor progression in cervical carcinoma." (PMID 37891885, 2023). "The primary aim of this clinical study is to determine the impact of angiotensin-converting enzyme (ACE) inhibitors, β-blockers and other risk factors such as the patient’s anatomical characteristics on ART emergence in patients with locally advanced cervical cancer treated by chemoradiotherapy." (PMID 33336040, 2020). "The primary aim of this clinical study is to determine the impact of ACE inhibitors, β-blockers and other potential risk factors such as the patient’s pelvic and anatomical characteristics on ART emergence in patients with locally advanced cervical cancer treated by chemoradiotherapy." (PMID 33336040, 2020).
clear cell renal cell carcinoma (3 papers, 2017 to 2025). "The expression of ACE, ACE2 and NEP/CD10 was highest in clear cell renal cell carcinoma (CCRCC) and papillary renal cell carcinoma (PRCC)." (PMID 28809959, 2017).
encephalitis (3 papers, 2020). An acute inflammatory process affecting the brain parenchyma. "In nervous system also, all RAS components are locally synthesized by different cell types, including astrocytes, microglia and neutrons, and ACE expression is increased in many neurological autoimmune diseases including encephalitis and multiple sclerosis." (PMID 32508938, 2020).
focal segmental glomerulosclerosis (3 papers, 2019 to 2024). A renal disorder characterized by sclerotic lesions in the glomeruli. "Our finding indicated that ACE (I/D) has moderate association with focal segmental glomerulosclerosis." (PMID 30333281, 2019).
fungal infections (3 papers, 2024 to 2025). "Sixty-eight other side effects not stated in any of the 10 Riskbase categories were documented by pharmacists during the MR service, which were most commonly cough caused by an ACE inhibitor and oral fungal infections caused by inhaled corticosteroids." (PMID 38434703, 2024). "His angiotensin-converting enzyme (ACE) level was found to be elevated at 359 U/L (reference range 13–100 U/L), and universal polymerase chain reaction (PCR) testing on the renal biopsy was found to be negative for acid-fast bacilli, bacterial, and fungal infection." (PMID 39359743, 2024).
Hodgkins lymphoma (3 papers, 1980 to 2023). A heterogeneous group of malignant lymphoid neoplasms of B-cell origin characterized histologically by the presence of Hodgkin and Reed-Sternberg (HRS) cells in the vast majority of cases. "Moreover, ACE was found to be elevated in some patients with Hodgkin’s lymphoma, which tends to complicate the diagnosis even further." (PMID 36672683, 2023).
hyperphosphatemia (3 papers, 2019 to 2025). Abnormally high level of phosphate in the blood. "Other studies suggest that hyperphosphatemia is linked to a suboptimal response to antiproteinuric treatments such as angiotensin-converting enzyme (ACE) inhibitors and low-protein diet." (PMID 31336909, 2019).
idiopathic nephrotic syndrome (3 papers, 2010 to 2019). Nephrotic syndrome for which no cause has been identified. "The aim of the study was to study the distribution of angiotensin-converting enzyme (ACE) gene insertion/deletion (I/D) polymorphism, and its association with steroid responsiveness in children with idiopathic nephrotic syndrome (INS)." (PMID 21655166, 2011). "Clinical and laboratorial findings of patients with idiopathic nephrotic syndrome subdivided according to use or not of medications that directly interfere with RAS: ACE inhibitors (ACEi) and ARB." (PMID 30514826, 2019).
infantile hemangioma (3 papers, 2015 to 2022). "The discovery of the central role of the renin-angiotensin system (RAS) in regulating stem cells in infantile hemangioma (IH) provides a plausible explanation for its spontaneous and accelerated involution induced by β-blockers and ACE inhibitors." (PMID 33634164, 2020).
joint diseases (3 papers, 2016 to 2022). "High blood ACE levels might increase bradykinin metabolism, thereby reducing the risk of knee OA because bradykinin involves the generation of pain, swelling, and cellular damage associated with joint disease." (PMID 27657933, 2016).
meningitis (3 papers, 2019 to 2025). A disorder characterized by acute inflammation of the meninges of the brain and/or spinal cord. "Cerebral spinal fluid (CSF) studies showed normal cell count, normal meningitis polymerase chain reaction panel, no growth on culture, normal α-fetoprotein level (to rule out hormone secreting germ cell tumor), no malignant cells, no oligoclonal bands, and normal angiotensin converting enzyme (ACE)." (PMID 31010318, 2019).
minimal change disease (3 papers, 2019 to 2025). "The beneficial effect of ACE inhibition on uEGF/uCreat differs significantly in children with minimal change disease compared to children with obvious signs of glomerular changes on kidney biopsy." (PMID 34900856, 2021). "Minimal change disease can occur as a renal complication of HIV infection and is usually treated effectively with steroid therapy in combination with ACE inhibitors and antiretroviral therapy." (PMID 39618540, 2025). "The response of uEGF/uCreat to ACE inhibition was absent in minimal change disease and contrasted with an impressive beneficial effect of ACE inhibition on uEGF/uCreat in FSGS and other proteinuric glomerulopathies." (PMID 34900856, 2021).
nasopharyngeal carcinoma (3 papers, 2017 to 2024). A carcinoma arising from the nasopharyngeal epithelium. "By inhibiting ACE, the levels of reactive oxygen species (ROS) are lowered, consequently diminishing the sensitivity to radiotherapy in cases of nasopharyngeal carcinoma." (PMID 38543146, 2024). "Similarly, ACE overexpression enhances the sensitivity of nasopharyngeal carcinoma cells to IR by increasing the level of ROS." (PMID 37371679, 2023).
nephrosclerosis (3 papers, 2014 to 2025). Hardening of the kidney due to infiltration by fibrous connective tissue (fibrosis), usually caused by renovascular diseases or chronic hypertension. "Studies in an animal model suggested that SLV306 had a similar efficacy to the angiotensin converting enzyme (ACE) inhibitor captopril in reducing proteinuria and preventing nephrosclerosis." (PMID 25131455, 2014). "Decreased ACE staining has also been reported in human beings with nephrosclerosis; however, it is noteworthy that renal mRNA and protein expression of ACE were not correlated in the same study." (PMID 40560995, 2025).
neuroblastoma (3 papers, 2017 to 2023). Neuroblastoma (NB) is the most common solid, extracranial childhood tumor. "It is reported that Aβ induced up-regulation of ACE in neuroblastoma cells, and neuronal ACE activity was increased in the brain of both AD model mice and AD patients with Braak stage, implying that ICV injection of Aβ might induce excess Ang II production in the brain." (PMID 28158298, 2017). "Two types of angiotensin-converting enzyme (ACE) inhibitors, lisinopril and benazepril HCl, were tested in neuroblastoma cells and found to upregulate low-density lipoprotein-receptor-related protein 1B (LRP1B) and 14-3-3 protein zeta/delta." (PMID 37630190, 2023). "A few proteins were identified to be more commonly up-regulated in ACE-inhibitor-treated neuroblastoma cells compared with nontreated cells." (PMID 37630190, 2023). "Thus, the lisinopril/Benazepril-HCl-mediated regulation found in neuroblastoma cells was predominantly independent of the ACE protein." (PMID 37630190, 2023).
nonalcoholic steatohepatitis (3 papers, 2016 to 2025). "Knowledge of the ACE level and ACE gene polymorphism in patients with NAFLD/nonalcoholic steatohepatitis (NASH) may be beneficial in terms of determining the treatment methods and in the follow-up of the disease progression." (PMID 29201746, 2016).
pertussis (3 papers, 2018 to 2025). A contagious bacterial respiratory infection caused by Bordetella pertussis. "Using the DGIdb database, we identified potential drug candidates for three biomarkers: HMOX1 (9 drugs, with Stannsoporfin achieving the highest score), TLR4 (22 drugs, with the pertussis vaccine scoring the highest), and ACE (59 drugs, with cilazapril scoring the highest)." (PMID 40282274, 2025).
Pleural effusion (3 papers, 2020 to 2025). The presence of an excessive amount of fluid in the pleural cavity. "In cats with pleural effusion, 11 received furosemide, three received ACE inhibitors and one received pimobendan before blood collection." (PMID 40999563, 2025).
proliferative diabetic retinopathy (3 papers, 2021 to 2025). Advanced retinopathy due to diabetes mellitus characterized by the formation of new vessels in the retina. "This is supported by the fact that proliferative diabetic retinopathy in humans increases ACE production in the aqueous humor." (PMID 37892765, 2023). "Stratification analyses on proliferative diabetic retinopathy (PDR) and non-proliferative diabetic retinopathy (NPDR) were also conducted for seven genetic variants: Ins/Del variant at ACE gene; SNP rs759853 at AKR1B1 gene; SNPs rs1570360, rs2010963, rs3025039, rs699947, and rs833061 at VEGF gene." (PMID 40116328, 2025).
retinopathy of prematurity (3 papers, 2015 to 2025). A bilateral retinopathy characterized by neovascularization, scarring, retinal detachment, and eventually blindness. "Retinopathy of prematurity (ROP) is a major cause of childhood blindness worldwide, linked to gene variants in the renin–angiotensin–aldosterone system, including angiotensin-converting enzyme (ACE) and angiotensin II receptor type 1 (AGTR1)." (PMID 39186201, 2025). "The clinical and experimental studies have revealed that ACE inhibition could be a potential target for arresting the progression of the retinopathy in diabetes and retinopathy of prematurity." (PMID 30460043, 2018). "Previous studies done in our lab has shown the presence multifold raised levels of renin angiotensin components in the vitreous of retinopathy of prematurity (ROP) patients and retinoprotective effect of the ACE inhibition in the animal model of ROP." (PMID 30460043, 2018). "Growing evidence links RAAS genes, including ACE and AGTR1, to retinopathy of prematurity (ROP)." (PMID 39186201, 2025).
Thrombocytosis (3 papers, 2013 to 2024). Increased numbers of platelets in the peripheral blood. "Blood workup revealed normocytic anemia, thrombocytosis and increased erythrocyte sedimentation rate (ESR) (110 mm/h), C-reactive protein (CRP) (33 mg/L) and angiotensin converting enzyme (ACE) (74 units/L)." (PMID 25494723, 2014).
thyroid cancer (3 papers, 2022 to 2023). "An increase in abundance (CHAO1, ACE) was observed in the thyroid cancer group and thyroid nodules group compared with the normal control group, though the differences showed little statistical significance among the three groups (ANOVA, p > 0.05)." (PMID 36034695, 2022).
Tinnitus (3 papers, 2016 to 2024). Tinnitus is an auditory perception that can be described as the experience of sound, in the ear or in the head, in the absence of external acoustic stimulation. "The use of thiazidic and potassium-sparing diuretics, ACE inhibitors, and calcium channels blockers was more prevalent in tinnitus patients." (PMID 27761128, 2016). "Data from this study demonstrated that the use of ACE inhibitors, thiazidic diuretics, potassium-sparing diuretics, and calcium channels blockers was more prevalent in the tinnitus hypertensive patients than in the control group." (PMID 27761128, 2016).
vesicoureteral reflux (3 papers, 2012 to 2017). Abnormal flow of urine from the urinary bladder back into the ureters. "However, research on the relationship of variation of polymorphic insertion/deletion ACE with the occurrence of the primary vesicoureteral reflux or threading kidney disease is inconclusive." (PMID 27988909, 2017). "The aim of this study was to establish the relationship of selected polymorphisms: 14094 polymorphism of the ACE, polymorphism rs1800469 of TGFβ-1, rs5443 gene polymorphism of the GNB3 and receptor gene polymorphism rs5186 type 1 AGTR1 with the occurrence of the primary vesicoureteral reflux." (PMID 27988909, 2017).